SDHB (succinate dehydrogenase complex iron sulfur subunit B)
Diseases named in the same sentence as SDHB in open-access papers (continued):
Sharing a sentence is not in itself a finding about the gene and the disease.
paraganglioma (continued). "Familial paragangliomas associated with SDHB and SDHD mutations resemble the carotid body growths that occur as a result of chronic hypoxia exposure in individuals living at high altitudes." (PMID 16103922, 2005). "Germline mutations of SDHD and SDHB are a major cause of the hereditary forms of the tumors paraganglioma and pheochromocytoma." (PMID 16288654, 2005). "Concerning SDH, its loss-of-function mutations have been detected mainly in two rare tumors, such as paraganglioma and pheochromocytoma, and are generally frequent on the two subunits SDHB and SDHC, whereas only few mutations affect the other subunits (SDHA and SDHD)." (PMID 38216942, 2024). "Furthermore, some malignant SDHB-mutated pheochromocytoma and paraganglioma were associated with hypermethylation of the MGMT promoter and responded to TMZ, as well as some SDH-deficient GIST tumors." (PMID 39201738, 2024). "Similarly, paragangliomas, pheochromocytomas and GISTs associated with germline mutation of SDHB, SDHC and SDHD have been previously shown to exhibit CIMP in comparison to tumors caused by mutations in other genes." (PMID 36455002, 2022). "SDHB is one of the major genes predisposing to paraganglioma/pheochromocytoma (PPGL)." (PMID 34452955, 2022). "Rare thoracic paragangliomas have been known to be associated with SDHB, SDHD, and VHL genes." (PMID 36138281, 2022). "ATRX was identified in the parathyroid adenoma tissue from patient B. Mutations in ATRX are associated with alternative lengthening of telomeres and have been shown to be associated with clinically aggressive behavior in SDHB mutated phaeochromocytoma and paraganglioma." (PMID 35323929, 2022). "Even paragangliomas and pheochromocytomas associated with succinate dehydrogenase subunit B (SDHB) variants, which may result in aggressive metastatic disease and fatal outcomes, show an overall 5-year survival of 76%-85%." (PMID 36178902, 2022). "Other genes and pathways implicated in CIMP include SDHB [succinate dehydrogenase complex iron sulfur subunit B] in paraganglioma, KRAS [KRAS proto-oncogene, GTPase], and activating BRAF [B-Raf proto-oncogene, serine/threonine kinase] mutations in colorectal cancer." (PMID 34074348, 2021). "Primary tumor sizes ≥5cm [HR 5.1 (1.7, 15.3), p=0.003] and average Ki-67 counts ≥3% of the primary tumor [HR 2.4 (1.1, 5.2), p=0.035] were independent predictors for recurrence of pheochromocytoma, while SDHB mutation [HR 4.6 (1.5, 13.9), p=0.007] was a predictor for paraganglioma recurrence." (PMID 34899602, 2021). "Interestingly, IDH1 and IDH2 mutated GBM, SDHB deficient pheochromocytoma and paraganglioma are more sensitive to temozolomide (TMZ), and IDH1/2 mutations are con-sidered a good prognostic factor." (PMID 34065551, 2021). "In recent years, studies have revealed that SDHB mutation predicts worse paraganglioma prognosis." (PMID 34579772, 2021). "Subsequently, SDHA and SDHB mutations were said to cause pheochromocytoma and paraganglioma." (PMID 34200553, 2021). "The Arg230His mutation in SDHB causes heritable pheochromocytoma/paraganglioma (PPGL)." (PMID 32859697, 2020). "Indeed, loss or markedly reduced SDHB expression has associated with familial cancer predisposition syndromes with affected individuals at increased risk for developing paragangliomas, pheochromocytomas (rare forms of adrenal tumors) and GISTs." (PMID 32570879, 2020). "SDHB mutations are found in 40% of patients with metastatic pheochromocytoma/paraganglioma." (PMID 30456751, 2018). "Furthermore, false-negative 123I-MIBG scintigraphy in patients with pheochromocytoma or paraganglioma has been associated with a more aggressive disease course and the presence of SDHB mutation." (PMID 30456751, 2018). "The typical age of presentation of paragangliomas due to SDHB mutations is 30 years." (PMID 29166454, 2017). "Therefore, all patients with metastatic phaeochromocytoma or paragangliomas should undergo SDHB mutation testing at the very least." (PMID 29166454, 2017).
paraganglioma (continued). "Especially SDHB mutations hve been shown to be associated with metastatic disease in paragangliomas and according to literature data about half of the patients with metastatic paragangliomas (especially those of sympathetic origin) display SDHB mutation." (PMID 29163802, 2017). "Interestingly, all the tumors with a SDHB or SDHD mutation in our series corresponded to paragangliomas and, in this subgroup of patients, combined measurement of CgA, WE-14 and EM66 also provided 100% sensitivity." (PMID 24523932, 2014). "Previous studies have shown that SDHB mutations predominantly predispose to abdominal or thoracic paragangliomas and adrenal PCC, but as Leiden is a national referral centre for HN-PGL, a referral bias may be operating." (PMID 19368708, 2009). "Carriers of SDHB variants may develop pheochromocytoma, extra-adrenal paraganglioma, and occasionally CBTs, with a metastasis incidence of approximately 23–25%, the highest among all genes associated with paraganglioma." (PMID 38339335, 2024). "Additionally, the Carney triad is characterized by multiple gastric GISTs, paragangliomas, and pulmonary chondromas with female predominance, and Carney–Stratakis syndrome that involves multiple gastric GISTs and paragangliomas is associated with SDHB dysfunction." (PMID 35809209, 2022). "Moreover, known epigenetic alterations triggered by mutated SDHB in paragangliomas suggest that underexpressed SDHB in oligodendrogliomas may support and possibly enhance the epigenetic reprogramming induced by the IDH-mutation." (PMID 29890994, 2018). "Inactivating mutations of the succinate dehydrogenase subunit B (SDHB) gene and the subsequent stabilization and activation of the hypoxia-inducible factor 2-alpha (HIF2α) unit are recognized hallmarks associated with the development of metastatic pheochromocytomas and paragangliomas (MPPG)." (PMID 30109021, 2018). "The “NGS and PPGL Study Group” also collected and classified variants in the SDHB gene, which is one of the major genes responsible for paraganglioma/pheochromocytoma predisposition (PPGL), leading to the creation of the SDHB variant database." (PMID 40041282, 2025). "SDHB expression was analyzed in pheochromocytoma, paraganglioma, and GIST from the patient using immunohistochemistry." (PMID 40242210, 2025). "The genomic landscape of hereditary SDHB-mutant pheochromocytomas (PC) and paragangliomas (PG) remains to be explored." (PMID 40097403, 2025). "Our analysis revealed that SDHB transcript levels in the paraganglioma sample from the CSS patient were comparable to those observed in other PPGLs with genetic alterations in cluster 1B and cluster 2 genes." (PMID 40242210, 2025). "Further genetic consultation is recommended if there is loss of SDHB expression, a family history of GIST, diagnosis of multiple GISTs, age of diagnosis less than 30 years, or association with paraganglioma." (PMID 39927693, 2025). "This case reported rare co-occurring variants in SDHB and KIF1B and unusual imaging findings of metastasis in paraganglioma." (PMID 40917352, 2025). "To further investigate SDHB expression, we performed Western blot analysis on tumor samples from the paraganglioma and pheochromocytoma of the patient with CSS." (PMID 40242210, 2025). "Pheochromocytomas and paragangliomas (PPGL) are classified as rare cancers but can be highly metastatic, particularly in individuals with inherited succinate dehydrogenase B (SDHB) mutations." (PMID 41155475, 2025). "Hereditary SDHB-mutant pheochromocytomas (PC) and paragangliomas (PG) are rare tumours with a high propensity to metastasize although their clinical behaviour is unpredictable." (PMID 38978571, 2024). "Approximately 25% to 35% of paragangliomas are often associated with hereditary conditions such as MEN type 2, von Hippel-Lindau syndrome, or mutations in the SDHB, SDHD, or RET gene." (PMID 39867070, 2024).
paraganglioma (continued). "PGL/PCC-related cancers were present only in three cases in SDHB showing gastrointestinal stromal tumor, SDH-deficient renal carcinoma, and paraganglioma." (PMID 38473309, 2024). "Carriers of genetic variations are screened from 18 years (10 in SDHB) to detect paragangliomas at the earliest stage for the optimal timing of intervention." (PMID 38473347, 2024). "Paraganglioma (PGL) is often linked with MEN, and its occurrence is commonly associated with metabolism-related mutation genes, which currently include SDHA, SDHB, SDHC, SDHD, and SDHAF2." (PMID 39591360, 2024). "It should be considered, that there is a high prevalence of occult paragangliomas in asymptomatic carriers of SDHD and SDHB gene mutations." (PMID 38144572, 2023). "Of note, mutations of SDH subunits, notably SDHB and SDHD, are detected in hereditary paragangliomas and pheochromocytomas." (PMID 37446354, 2023). "Most cases of hereditary paraganglioma are accounted for by pathogenic variants in SDHD, SDHB, and SDHC, VHL, and NF1." (PMID 38003974, 2023). "Germline mutations in SDHx are a major cause of phaeochromocytoma and paragangliomas but inheritance patterns and risks differ between genes, and the penetrance of germline SDHA mutations is much lower than for SDHB, SDHC or SDHD." (PMID 35441217, 2022). "Five individuals (8%) from five families, all of whom received an SDHx variant (4 SDHB, 1 SDHD), had a personal history (2 with a GIST (2 SDHB), 2 with a paraganglioma (1 SDHD, 1 SDHB), and 1 with paragangliomas and renal cell carcinoma (1 SDHB))." (PMID 35668420, 2022). "Prior studies have shown that paragangliomas, pheochromocytomas, and gastrointestinal stromal tumors from patients with inherited mutations in SDH genes, particularly SDHB, have increased DNA methylation in their tumors." (PMID 35628470, 2022). "In preliminary research, SDHC, SDHB, and SDHD have been mentioned as mutated subunits of SDH in paragangliomas, and subsequent research confirmed the mutation in other parts, including SDHAF2 and SDHA." (PMID 36286449, 2022). "The weight of the evidence to attach to observation of a novel rare missense variant in SDHB or SDHD in individuals with the rare neuroendocrine tumors, pheochromocytomas and paragangliomas (PCC/PGL), is uncertain." (PMID 34906457, 2022). "Germline mutations in SDHA, SDHB, SDHC, and SDHD (collectively, SDHx) are associated with the development of PRL- and GH-secreting adenomas, pheochromocytomas, and/or paragangliomas, a syndrome named 3P association." (PMID 35743266, 2022). "We describe the long-term culture of chiefly head and neck paragangliomas using primary tumour tissue from anonymous donors who carried succinate dehydrogenase subunit B (SDHB), subunit C (SDHC), subunit D (SDHD) or undefined gene variants." (PMID 36178902, 2022). "Mutations in the SDHB subunit of succinate dehydrogenase (SDH) cause pheochromocytomas and paragangliomas (PCCs/PGLs) and predispose patients to malignant disease with poor prognosis." (PMID 35008989, 2022). "Germline mutation of the succinate dehydrogenase subunit genes, SDHA, SDHB, SDHC or SDHD, is associated with increased risk for paraganglioma (PGL), pheochromocytoma (Pheo), gastrointestinal stromal tumor (GIST) and renal cell carcinoma." (PMID 36455002, 2022). "One individual with an SDHB pathogenic variant (3% of participants with SDHx result and 7% with SDHB result via GSC) was diagnosed with a left head and neck paraganglioma post-result disclosure." (PMID 35668420, 2022). "The hypermethylation changes the expression profile of specific genes, leading for instance to the activation of the EMT program, as demonstrated in pheochromocytomas and paragangliomas knocked-down for SDHB." (PMID 34065551, 2021). "In HNPGLs, Chromogranin A correctly predicts the result of paraganglioma surveillance more often in patients with SDHB compared with those with SDHD (77% vs. 22%, p = 0.003) and has less added benefit to standard surveillance." (PMID 35054195, 2021).
paraganglioma (continued). "Approximately 20% of patients diagnosed with a phaeochromocytoma or paraganglioma carry a germline mutation in one of the succinate dehydrogenase (SDHx) genes (SDHA, SDHB, SDHC and SDHD), which encode the four subunits of the SDH enzyme." (PMID 34021277, 2021). "These two cohorts were combined thereafter, and a total of 58 samples from patients with pheochromocytoma or paraganglioma were stained for SDHB." (PMID 34356532, 2021). "Germline mutations of SDHB, SDHC, and SDHD genes are responsible for approximately 50% of hereditary paragangliomas and pheochromocytomas." (PMID 34012423, 2021). "CSS by definition is due to SDHB, SDHC, and SDHD mutations and is characterized by the combination of GIST and paraganglioma inherited in an apparently autosomal dominant manner and with incomplete penetrance." (PMID 35059314, 2021). "The pooled incidence for malignant paragangliomas is about 8% in SDHD mutation carriers, whilst for SDHB, it can be as high as 41%." (PMID 34072806, 2021). "Mutations in SDHB, SDHC, and SDHD have been implicated in causing two rare tumors in the autonomic nervous system known as paraganglioma (PGL) and pheochromocytoma (PCC)." (PMID 33153035, 2020). "Another study on SDHB, SDHC, and SDHD gene mutation analysis in a large cohort of patients with a personal or family history of paragangliomas/pheochromocytomas was performed." (PMID 32948182, 2020). "Mutations in VHL, RET, NF1, SDHB, and SDHD account for 90% of all pheochromocytomas and paragangliomas." (PMID 32266384, 2020). "SDHB (10.3%) and SDHD (8.9%) mutations are the most frequent germline mutations in pheochromocytoma and paragangliomas." (PMID 32266384, 2020). "SDHb related changes in pheochromocytomas and paragangliomas are coupled to bioenergetic reprogramming where decrease in complex II of the ETC caused compensatory increase in Complexes I, III and IV with concomitant decrease in ATP levels." (PMID 31849832, 2019). "This pattern has been reported 3.7–11.5% of paragangliomas/pheochromocytomas and was frequently identified in cases with SDHD and SDHB mutations." (PMID 30971719, 2019). "SDHB immunonegativity has been reported in pheochromocytoma/paraganglioma, GISTs, RCCs, PAs, pancreatic NETs, prostate cancer, stomach cancer, and testicular seminoma." (PMID 30971719, 2019). "VHL, RET, NF1, SDHB, and SDHD are major susceptibility genes, accounting for 90% of familial pheochromocytomas/paragangliomas, whereas TMEM127, SDHA, SDHC, SDHAF2, and MAX are minor susceptibility genes responsible for 10% of these tumors." (PMID 30456751, 2018). "Known pathogenic variation in SDHB/RET, BRCA1/2, and MMR genes is thought to be responsible for a subset of pheochromocytoma and paraganglioma, breast, ovarian, colon, and uterine cancers in TCGA." (PMID 30217226, 2018). "Succinate dehydrogenase subunit B and D (SDHB and SDHD) mutations represent the most frequent cause of hereditary pheochromocytoma and paraganglioma (PPGL)." (PMID 30106970, 2018). "Accordingly, human HEK293 cells treated with siRNA against the SDH component SDHB showed increased susceptibility to the LDH inhibitor oxamate, suggesting LDH as a potential target in paraganglioma therapy." (PMID 29905792, 2018). "The prevalence of germline mutations in SDHB, SDHC, SDHD, VHL and MAX in PCC and paraganglioma patients is, respectively, 10%, 1%, 9%, 7%, and 1%." (PMID 29768630, 2018). "Analysis of tumor tissue from the pituitary adenomas and the pheochromocytomas/paragangliomas demonstrated SDHB LOH in three pituitary adenomas and LOH of MEN1 in two pheochromocytomas." (PMID 30456751, 2018). "SDHB mutations also activate EMT-inducing transcription factors, such as Snail and Slug, and lead to invasive human metastatic pheochromocytomas and paragangliomas, indicating that SDHB mutations are linked to the induction of EMT in these tumors." (PMID 30671168, 2018).
paraganglioma (continued). "To investigate the extent and nature of chromosome 11 loss across the various paraganglioma subgroups, we assembled a panel of 26 SDHD, 13 SDHB, and 8 VHL-related PGLs/PCCs." (PMID 28099933, 2017). "Germline mutations in the four genes encoding SDH subunits (SDHA, SDHB, SDHC and SDHD) are linked to the development of neuroendocrine tumors such as pheochromocytomas and paragangliomas." (PMID 28911113, 2017). "Germline mutations in the succinate dehydrogenase complex genes SDHB, SDHC, and SDHD predispose to pheochromocytomas and paragangliomas." (PMID 27279923, 2016). "Mutations in the CII subunit genes SDHA, SDHB, SDHC and SDHD have also been associated with paragangliomas and pheochromocytoma." (PMID 26839416, 2016). "Here, we examine the SDHB, SDHC, and SDHD mutation spectrum in the Danish population by screening of 143 Danish pheochromocytoma and paraganglioma patients." (PMID 27279923, 2016). "Germline mutations in SDHA, SDHB, SDHC, SDHD, and SDHAF2 cause paraganglioma/pheochromocytoma (PGL/PCC)." (PMID 26472283, 2015). "In 2006, a study comprising a larger number of patients with pheochromocytoma/paraganglioma showed that 33% of the patients carried germline mutations in one of the following genes: VHL, RET, NF1, SDHB, and SDHD." (PMID 24899893, 2014). "Previous studies demonstrated that SDHB-, SDHC-, and SDHD-related paragangliomas and GIST all show loss of SDHB immunohistochemical expression." (PMID 22974104, 2012). "A glycolytic profile unifies a group of pheochromocytomas and paragangliomas (PHEOs/PGLs) with distinct underlying gene defects, including von Hippel-Lindau (VHL) and succinate dehydrogenase B (SDHB) mutations." (PMID 22859959, 2012). "The persistent expression of SDHA protein in SDHA non-mutated GIST is in accordance with previous studies which showed consistent SDHA protein expression in SDHB-, and SDHD-mutated paraganglioma." (PMID 22974104, 2012). "Heterozygous germline mutations in SDHA, SDHB, SDHC, and SDHD cause hereditary paragangliomas and pheochromocytomas, and germline mutations in SDHB and SDHC were found to be associated with gastrointestinal stromal tumors." (PMID 22995659, 2012). "Although nearly all familial paraganglioma in the Netherlands is accounted for by the Dutch SDHD founder mutations p.Asp92Tyr and p.Leu139Pro, several Dutch families carrying an SDHB mutation were recently identified." (PMID 19368708, 2009). "Germline mutations of the tumor suppressor genes SDHB, SDHC and SDHD play a major role in hereditary paraganglioma and pheochromocytoma." (PMID 19368708, 2009). "Paragangliomas may be hereditary and can be associated with familial paraganglioma, neurofibromatosis type 1, von Hippel-Lindau disease, the Carney triad, multiple endocrine neoplasia type 2, and mutations of the succinate dehydrogenase genes (SDHB, SDHC, and SDHD)." (PMID 17683569, 2007). "To confirm this finding, we performed immunostaining of SDHB in pheochromocytomas or paragangliomas representative of the various genetic syndromes using available paraffin-embedded material." (PMID 16103922, 2005). "Neither the 24 SDHB-related cases nor the 2 SDHA variant carriers developed a paraganglioma after a median of 4.83 and 5.92 years of follow-up, respectively." (PMID 39881751, 2025). "The SDHx family, a well-studied group of tumor suppressors, may have a significant impact on the metastatic behavior of paragangliomas and pheochromocytomas, with SDHB already incorporated into certain tumor scoring systems." (PMID 40852478, 2025). "Wild type GIST driven by germline mutations in SDHB, SDHC, or SDHD subunits is a component of the Carney-Stratakis syndrome, an inherited predisposition syndrome characterized by the presence of GIST and paraganglioma." (PMID 36980917, 2023). "The SDHB-deficient IHC on the myocardial valvular biopsy confirmed that the germline variant is likely an inactivating first hit in the SHDC gene, and is likely involved in this patient’s paraganglioma." (PMID 36091175, 2022).